C11orf87 (chromosome 11 open reading frame 87)
Synonyms: LOH11CR1A; LOC399947; NEURIM1
Tractability: Antibody: UniProt predicts a signal peptide or a membrane-spanning region.
Gene: Protein-coding gene on chromosome 11 (109,422,190 to 109,429,167, forward strand). Ensembl gene ENSG00000185742.
Subcellular location: Membrane
Gene Ontology:
Molecular function: protein binding
Cellular component: membrane
Genetic constraint (gnomAD): Loss-of-function variants: 3 observed, 9.31 expected, observed/expected ratio (o/e) 0.32, 90% interval 0.15 to 0.83. That is too few expected variants to judge how well the gene tolerates losing a copy. Missense variants: 256 observed, 283.51 expected, observed/expected ratio (o/e) 0.9, 90% interval 0.81 to 1. Synonymous variants: 124 observed, 129.74 expected, observed/expected ratio (o/e) 0.96, 90% interval 0.82 to 1.11.
Homologues: Orthologues: chimpanzee C11H11orf87 (99% identical), macaque C14H11orf87 (98% identical), rabbit C11orf87 (91% identical), pig C11orf87 (89% identical), rat C8h11orf87 (89% identical), dog C11orf87 (88% identical), mouse AI593442 (87% identical), tropical clawed frog c2h11orf87 (40% identical), zebrafish si:dkey-35i13.1 (31% identical).
Diseases named in the same sentence as C11orf87 in open-access papers:
C11orf87 is named in the same sentence as 9 diseases in open-access papers, as found by Europe PMC text mining. Sharing a sentence is not in itself a finding about the gene and the disease. The quoted sentences say what the papers report.
gastric cancer (1 paper, 2021). A primary or metastatic malignant neoplasm involving the stomach. "Importantly, methylation of C11orf87 may act as a novel diagnostic biomarker for gastric cancer." (PMID 33886682, 2021). "In this study, we further identified a putative STAT3 target, C11orf87, showing differential hypomethylation in gastric cancer cell lines and patient samples with lower STAT3 activation status." (PMID 33886682, 2021). "However, the functional and clinical role of C11orf87 in gastric cancer warrants further investigation." (PMID 33886682, 2021). "As the methylation wasn’t crucial for controlling C11orf87 expression, we then investigated whether the methylation of C11orf87 could serve as a biomarker for gastric cancer." (PMID 33886682, 2021). "Interestingly, our results suggested that C11orf87 methylation can be a biomarker for early detection and disease prognosis in gastric cancer." (PMID 33886682, 2021). "Indeed, treatment of STAT3 inhibitor, JSI-124, resulted in a downregulation of C11orf87 expression in AGS gastric cancer cells." (PMID 33886682, 2021). "Herein, we postulated that hypermethylation of C11orf87 may serve as a “vestigial marker” for constitutive activation of STAT3 in gastric cancer." (PMID 33886682, 2021). "In this study, by using DNA methylation microarray, we identified a potential STAT3 target, C11orf87, showing promoter hypomethylation in gastric cancer patients with lower STAT3 activation and AGS gastric cancer cell lines depleted with STAT3 activation." (PMID 33886682, 2021). "In the current study, by DNA methylation microarray, we further identified a potential STAT3 target, C11orf87, showing hypomethylation in AGS gastric cancer cells depleted with STAT3 and patients with lower STAT3 activation." (PMID 33886682, 2021). "Although C11orf87 methylation is independent of its expression, ectopic expression of a constitutive activated STAT3 mutant upregulated its expression in gastric cancer cell line." (PMID 33886682, 2021).
schizophrenia (1 paper, 2020). A major psychotic disorder characterized by abnormalities in the perception or expression of reality. "The genes HGF, PRRT2, EGR1, EGR3, C11orf87, TLR3 and PLEKHH2 have been reported in either genetic analysis or gene expression analysis of schizophrenia, and were all upregulated in fibroblasts from patients in our study." (PMID 31959813, 2020).
cancer (2 papers, 2021 to 2025). A tumor composed of atypical neoplastic, often pleomorphic cells that invade other tissues. "A majority of the previously unpublished genes have been associated with tumorigeneses and tumor-suppressor pathways, primarily in cancer phenotypes, including: SLC16A11, POLR2A, C11orf87, and SLC12A747–52." (PMID 40050615, 2025). "However, the involvement of C11orf87 in human cancer has not been characterized." (PMID 33886682, 2021).
C11orf87 also shares sentences with these, for which no sentence is quoted: colon adenocarcinoma (1 paper); esophageal carcinoma (1); pancreatic adenocarcinoma (1); prostate carcinoma (1); rectum adenocarcinoma (1); tumor (1).